SOCS1 (suppressor of cytokine signaling 1)
Diseases named in the same sentence as SOCS1 in open-access papers (continued):
Sharing a sentence is not in itself a finding about the gene and the disease.
colorectal cancer (34 papers, 2007 to 2025). A primary or metastatic malignant neoplasm that affects the colon or rectum. "The hypermethylation of the suppressor of SOCS1 was related to colitis-associated colorectal cancer progression." (PMID 38891888, 2024). "Furthermore, GO ontology analysis indicated that differential SOCS1 expression was associated with pancreatic cancer and colorectal cancer and affected cellular processes related to the cell cycle, apoptosis and phagosomes." (PMID 32096766, 2020). "In an earlier study, SOCS1 was identified as a tumor suppressor in certain colorectal cancer patients." (PMID 35137551, 2022). "In cancers, aberrant SOCS1 methylation was observed in cancerous specimens, such as in multiple myeloma, pancreatic ductal adenocarcinoma, and in young patients with colorectal cancer." (PMID 34679523, 2021). "Similar to our result, other researchers have indicated that histone deacetylase inhibitor TSA suppresses the growth of colorectal cancer cells, and induces apoptosis through SOCS1 and SOCS3 upregulation and JAK2/STAT3 signaling inhibition." (PMID 34319031, 2021). "Promoter methylation and expression of SOCS-1 affect clinical outcome and epithelial-mesenchymal transition in colorectal cancer." (PMID 28915645, 2017). "Upon the analysis of gene expression data sets of human colorectal cancer specimens, SOCS1 expression is found elevated in tumors than normal epithelium." (PMID 27613835, 2016). "Furthermore, miR-155 derived from colorectal cancer Exo stimulates the activation of fibroblasts through the SOCS1/JAK2/STAT3 signaling pathway." (PMID 40486266, 2025). "Integrating miR-155, VEGF, and immune-regulatory markers (e.g., SOCS1, BCL-6, IL-13RA1) into biomarker-based colorectal cancer detection models could enhance early detection and risk assessment." (PMID 41345725, 2025). "Moreover, trichostatin A (TSA) leads to the hyperacetylation of histones associated with SOCS1 and SOCS3 promoters, which significantly downregulates JAK2/STAT3 signaling in colorectal cancer cells." (PMID 35611249, 2022). "Spontaneous colorectal cancer was also seen in SOCS1 knockout mice in an IFNγ-dependent manner." (PMID 24757565, 2014). "However, the role of SOCS1 in colorectal cancer (CRC) remains understudied and controversial." (PMID 26391193, 2015). "Aberrant expression of SOCS1 and SOCS3 has been described in human colorectal cancer, where SOCS3 overexpression inhibits proliferation, migration and invasiveness of tumor cells, while SOCS1 overexpression has pro-oncogenic activity." (PMID 35413796, 2022). "TSA increases the expression of SOCS1 and SOCS3 in human colorectal cancer cells and suppresses CRC growth." (PMID 28228755, 2017). "Trichostatin A (TSA), a histone deacetylase inhibitor, suppresses JAK2/STAT3 signaling by increasing the expression of SOCS1 and SOCS3 in human colorectal cancer cells and manipulates the expression of SOCS proteins in tumors." (PMID 28228755, 2017). "The Laird methylation marker panel used to determine CIMP status of colorectal cancers consists of the CACNA1G, IGF2, NEUROG1, RUNX3 and SOCS1 genes." (PMID 20846368, 2010). "We obtained 920 colorectal cancer specimens and quantified DNA methylation in the 8 CIMP-specific gene promoters (CACNA1G, CDKN2A, CRABP1, IGF2, MLH1, NEUROG1, RUNX3 and SOCS1) by MethyLight technology." (PMID 17474983, 2007). "Notably, butyrate generated by Faecalibacterium prausnitzii in murine colorectal cancer models, acts as a histone deacetylase (HDAC) inhibitor, leading to acetylation of histone proteins at the suppressor of cytokine signaling 1 (SOCS1) promoter." (PMID 41472726, 2025). "We obtained 401 colorectal cancer specimens and successfully quantified DNA methylation in eight CIMP-specific gene promoters (CACNA1G, CDKN2A, CRABP1, IGF2, MLH1, NEUROG1, RUNX3, and SOCS1) using MethyLight technology." (PMID 31690257, 2019).
colorectal cancer (continued). "We have chosen colon cancer cells with SOCS1 expression at intermediate levels through initial screening of various colorectal cancer cell lines (data not shown)." (PMID 27613835, 2016). "Utilizing MethyLight technology (real-time PCR), we quantified DNA methylation in 8 CIMP-specific promoters {CACNA1G, CDKN2A (p16), CRABP1, IGF2, MLH1, NEUROG1, RUNX3 and SOCS1} in 758 non-MSI-high colorectal cancers obtained from two large prospective cohorts." (PMID 17474983, 2007).
autoimmune disease (32 papers, 2010 to 2025). A disorder resulting from loss of function or tissue destruction of an organ or multiple organs, arising from humoral or cellular immune responses of the individual to their own tissue constituents. "For SOCS1 mimetics, robust evidence is available from autoimmune disease models such as lupus, and mechanistic studies in arthritis models (e.g., SOCS1-deficient mice) consistently support their protective role." (PMID 41393140, 2025). "An increasing number of studies have demonstrated that SOCS1 is associated with a wide range of acute or chronic inflammatory diseases, as well as autoimmune disorders." (PMID 39851515, 2025). "In humans, SOCS-haploinsufficiency (SOCS1-HI) presents a diverse clinical spectrum, encompassing autoimmune diseases, infection susceptibility, and cancer." (PMID 38711523, 2024). "The ability of SOCS1 to limit cytokine signaling positions it as an important immune checkpoint, as evidenced by the detection of detrimental SOCS1 variants in patients with cytokine-driven inflammatory and autoimmune disease." (PMID 38947335, 2024). "Since then, over 10 families with SOCS1-HI have been reported, presenting a broad phenotypic spectrum from autoimmune diseases, autoinflammatory manifestations to infection susceptibility and cancer." (PMID 38711523, 2024). "Reduced levels of SOCS1, a critical regulator of cytokine signaling, is associated with several autoimmune diseases." (PMID 39867889, 2024). "Alterations in SOCS1 activity are implicated in autoimmune diseases such as psoriasis, systemic lupus erythematosus, recurrent uveitis, and cancer." (PMID 37916165, 2023). "Dysregulated expression of SOCS3 has been frequently observed in various forms of inflammatory disorders, such as rheumatoid arthritis and Crohn’s disease, with SOCS1 haploinsufficiency shown to predispose to early onset autoimmune disease." (PMID 36969252, 2023). "SOCS1 haploinsufficiency leads to early-onset autoimmune diseases associated with the cytokine hypersensitivity of immune cells." (PMID 34121041, 2021). "Here the authors identify and characterize heterozygous SOCS1 mutations in 10 patients from 5 unrelated families with autoimmune diseases." (PMID 33087723, 2020). "In the gene-rich region of chromosome 16p13, several autoimmune disease-associated SNPs have also been identified in the neighboring SOCS1 and CIITA genes, as well as in intergenic regions." (PMID 23439554, 2013). "These newly discovered functions of SOCS1 help to explain theincreased susceptibility of Socs1 null mice to develop cancer aswell as their propensity to develop autoimmune diseases." (PMID 20622265, 2010). "The CLEC16A locus, encompassing SOCS1, is now associated with 21 autoimmune diseases." (PMID 38022642, 2023). "Notably, suppressor of cytokine signaling 1 (SOCS1), which naturally limits the activation of Jak2 through binding interactions, is often deficient in autoimmune disease patients." (PMID 35505065, 2022). "Hence, SOCS1 haploinsufficiency causes a dominantly inherited predisposition to early onset autoimmune diseases related to cytokine hypersensitivity of immune cells." (PMID 33087723, 2020). "However, a germline SOCS1 variant of unknown significance (p.Q210H, rs11549428) was found in one individual with autoimmune disease-related PCNSL." (PMID 37495858, 2023). "miR-155 potentiates the development of both regulatory T cells (Treg) and T helper 17 (Th17) cell subsets while augmenting IL-17A secretion through SOCS1 targeting, thereby influencing immune tolerance and autoimmune diseases." (PMID 40282426, 2025). "The mechanism of action of SOCS-1 and its potential therapeutic role in the prevention and treatment of autoimmune diseases have been reported." (PMID 38791600, 2024). "Further studies of the cross-talk between SOCS1 and the SOCS family members is needed to cement SOCS1 as a useful therapeutic target for autoimmune diseases and cancers." (PMID 39676878, 2024).
autoimmune disease (continued). "SOCS1 helps to control inflammation, immune responses, and cell differentiation in various autoimmune diseases." (PMID 38022642, 2023). "The gene of SOCS1 was found to be targeted by insulin and aldesleukin, of which both have been applied to treat autoimmune diseases, including systemic lupus erythematosus, type 1 diabetes mellitus, and HIV." (PMID 34872583, 2021). "Jakinibs have gained a great deal of attention in the last two decades for their efficacy in cancer and autoimmune diseases and we believe SOCS1 mimetics would be a great addition to the arsenal of jakinibs." (PMID 31105556, 2019). "SOCS1-/- Dendritic cells have an increased sensitivity to LPS and can often result in system autoimmune diseases." (PMID 31105556, 2019). "The use of the SOCS1 mimetics in treatment of autoimmune diseases in mouse models is presented under a separate section below." (PMID 25954276, 2015). "Both CIITA and SOCS1 are compelling candidate genes for autoimmune diseases as their functions in immune cells are well established." (PMID 26203907, 2015). "An SOCS1 mimetic plays an important role in inhibiting the inflammatory aspect of autoimmune diseases such as multiple sclerosis as pointed out in the fourth review." (PMID 25601864, 2014). "The pathogenic mechanisms of autoimmune diseases are complex, and SOCS proteins, particularly SOCS1, SOCS2, SOCS3, and SOCS5, regulate cytokine receptor signaling through distinct mechanisms, thereby participating in the development and progression of autoimmune diseases." (PMID 40755762, 2025). "The SOCS1 gene has been implicated in multiple autoimmune disorders, though variants in the gene have not been identified as causal." (PMID 38947339, 2024). "SOCS1, which limits JAK2 activation, is often deficient in autoimmune disease patients." (PMID 38022642, 2023). "Accumulated evidence has demonstrated the important role of SOCS1 in autoimmune disease." (PMID 35585676, 2022). "In T cell-specific SOCS1-conditional knockout mice, SOCS1-deficient CD4+ naïve T cells mostly differentiated into Th1 cells, and Th17 differentiation was strongly suppressed; these mice eventually developed a lupus-like autoimmune disease." (PMID 29085365, 2017). "Translationally, it suggests a role for SOCS1 mimetics in treating inflammatory and autoimmune diseases where Ubc13-like dysregulation may be involved." (PMID 25954276, 2015). "Thus, given the importance of the IFNs in Sjogren’s syndrome, it would seem that it would be a candidate for potential SOCS1 mimetic therapy based on the experience with other autoimmune diseases." (PMID 25601864, 2014). "However, this review has several limitations: current research on the SOCS family and autoimmune diseases predominantly focuses on SOCS1 and SOCS3, with insufficient comprehensive discussion regarding the specific roles of each component within the molecular structure of SOCS proteins." (PMID 40755762, 2025). "In infection models and autoimmune disease models, EZH2 inhibits the expression of genes and signaling pathways involved in anti-inflammatory function, such as PPARγ, SOCS1, STAT6, etc.." (PMID 35432300, 2022). "SOCS1 and SOCS3 have been reported to be aberrantly expressed in some autoimmune diseases and involved in regulating the functions of diverse immune cells." (PMID 34616359, 2021). "SOCS1 is a negative regulator of JAK/STAT, which plays an important role in inflammation, autoimmune diseases and other diseases." (PMID 34600581, 2021). "SOCS proteins, especially SOCS1 and SOCS3, are often dysregulated in a wide variety of autoimmune diseases." (PMID 28418931, 2017). "New substrates of SOCS1 are still being discovered, and while targeting this protein has potential in many immune disorders, not all effects of SOCS1 are advantageous in the context of autoimmune diseases." (PMID 39676878, 2024).
autoimmune disease (continued). "SOCS1 is one of the most important members of the SOCS protein family which is a negative regulator of JAK/STAT signaling and mainly exerts its effects on inflammation, autoimmune diseases and other diseases through the JAK/STAT pathway." (PMID 34600581, 2021). "Studies have revealed aberrant SOCS1 and SOCS3 expressions in diverse autoimmune diseases." (PMID 34616359, 2021). "While SOCS1 has promising potential in many disorders, it should be noted that new targets and actions of SOCS1 are still being discovered and not all the effects of this protein are beneficial in autoimmune diseases and cancer." (PMID 31105556, 2019). "In addition, several experimental models of inflammatory and autoimmune diseases have highlighted the importance of SOCS1 in regulating T cell activation, acting as a “non-classical” checkpoint and a tumor suppressor." (PMID 39596207, 2024). "In mouse models, we have shown that the deletion of SOCS1 or NR4a in T cells regresses cancers due to strong tumor immunity.96,117) We will continue our research in pursuit of the application of SOCS and NR4a to the treatment of autoimmune diseases and cancers in humans." (PMID 34121041, 2021). "Notably, within autoimmune disorders, multiple SOCS proteins (SOCS1, SOCS3, SOCS5, and CIS) function as potent negative regulators significantly contribute to the underlying mechanisms driving the diseases’ progression." (PMID 38022642, 2023).
Autoimmunity (32 papers, 2009 to 2025). The occurrence of an immune reaction against the organism's own cells or tissues. "This variant has been previously reported in family C of a prior study, where a similar frameshift mutation in the SOCS1 gene was associated with early-onset autoimmunity, including Evans syndrome and lymphoproliferative manifestations." (PMID 40755921, 2025). "Excessive IFN-γ can lead to tissue damage and autoimmunity as illustrated by the severe inflammatory disease in mice deficient in suppressor of cytokine signaling 1 (SOCS1), one of several known attenuators of IFN-γ expression." (PMID 33763084, 2021). "We found that SOCS1 haploinsufficiency is associated with dominantly inherited early onset autoimmunity and lymphoproliferation in ten patients from five unrelated families." (PMID 33087723, 2020). "In conclusion, our results show that SOCS1 haploinsufficiency is a recognized cause of early onset autoimmunity." (PMID 33087723, 2020). "In Tregs, SOCS1 signaling controls IFNγ production and defects in SOCS1 activity are thought to underlie autoimmunity and susceptibility to endotoxemia [reviewed in Ref." (PMID 27621733, 2016). "We observed that SOCS1-deficient T cells induce lupus-like autoimmunity including spontaneous dermatitis, splenomegaly, and lymphadenopathy with elevated ds-DNA antibodies." (PMID 25133199, 2014). "Early-onset autoimmunity associated with SOCS1 haploinsufficiency." (PMID 37848930, 2023). "Treatment of autoimmunity associated with SOCS1+/- may therefore require a broader immunosuppressive approach." (PMID 34421895, 2021). "Therefore, SOCS1 deficiency highly contributes to the imbalance of different Th cells and subsequent autoimmunity." (PMID 29085365, 2017). "It is also possible that impaired SOCS1 expression may underlie the pathogenesis of other human liver diseases induced by infection, autoimmunity, drugs, and alcohol." (PMID 20862390, 2010). "Suppressor of cytokine signaling 1 (SOCS1) haploinsufficiency is a recently described inborn error of immunity characterized by autoimmunity, inflammation, lymphoproliferation, and increased infection susceptibility." (PMID 41249727, 2025). "It is therefore important to highlight how the coexistence of autoimmunity, autoinflammation, and atopy can be explained by the versatility of SOCS1 in regulating the inflammatory response." (PMID 41249727, 2025). "For this reason, it is important to raise awareness among clinicians to consider SOCS1 haploinsufficiency in patients with recurrent fevers who develop other complications over time, especially multiple autoimmunity." (PMID 41249727, 2025). "We demonstrated that SOCS1+/- patient cells showed an increased activity in the FAK – AKT – RS6K pathway further explaining the accumulation of autoimmunity." (PMID 34421895, 2021). "SOCS1 also influences the differentiation and function of dendritic cells (DCs) to suppress systemic autoimmunity and maintain their tolerogenic phenotype." (PMID 34604264, 2021). "These variable phenotypes with autoimmunity are evident from the overview of SOCS1 haploinsufficiency phenotypes which demonstrates the clinical spectrum spans from autoimmunity to infections and malignancy." (PMID 34421895, 2021). "Our observations in SOCS1 insufficiency provide mechanistic insight into the development of autoimmunity induced by cytokine hypersensitivity in immune cells following the loss of a downregulatory element." (PMID 33087723, 2020). "In this review, we describe the mechanism of action of SOCS1 and its potential therapeutic role in the prevention and treatment of autoimmunity and cancer." (PMID 31105556, 2019). "Since SOCS1 has a profound role in T cell homeostasis, it is a prominent player in both autoimmunity and cancer." (PMID 31105556, 2019).